NGF (nerve growth factor)
Diseases named in the same sentence as NGF in open-access papers (continued):
Sharing a sentence is not in itself a finding about the gene and the disease.
tumor (continued). "Peripheral nerves form a complex tumor microenvironment composed of multiple cell types and factors, including nerve growth factor (NGF)." (PMID 38694509, 2024). "In this narrative review, we comprehensively explored the intricate molecular mechanisms through which inflammation and NGF impact tumor cell growth, survival, and death." (PMID 38392180, 2024). "The present study has revealed that during the process of T‐cell infiltration from adjacent tissues to tumor tissues, an inefficiency in NGF‐NGFR communication occurs in the tumor tissues." (PMID 38204220, 2024). "Research using Dclk-positive tuft cells demonstrates that cholinergic stimulation of the gastric epithelium induces nerve growth factor (NGF) expression, which promotes the development of neoplasia." (PMID 38791353, 2024). "This narrative report aims to provide a summary and subsequent review of literature evidence on the role of NGF and its role in regulating tumor cell growth and death as an inflammatory factor." (PMID 38392180, 2024). "Knowing that NGF blockade significantly reduced tumor proliferation, nociception, and weight loss in preclinical oral SCC models, anti-NGF is a promising treatment strategy to treat oral SCC progression, pain, and cachexia." (PMID 39906323, 2024). "Researchers have also demonstrated that NGF secreted by tumors stimulates nerve regeneration and plays a key role in promoting the survival, motility, and invasion of tumor cells." (PMID 39247831, 2024). "The cell‐to‐cell communication assay conducted in the present study revealed that NGF‐NGFR communication was the only signal in the tumor tissues of HCC patients." (PMID 38204220, 2024). "The intriguing aspect of NGF’s contribution to cancer lies in its dual role, acting as both an oncogenic factor, fueling tumor cell growth, and as a pro-apoptotic mediator, promoting tumor cell death under certain circumstances." (PMID 38392180, 2024). "In the case of serine deprivation, PDAC cells express and secrete more NGF by upregulating its translation, thereby enhancing the movement of axons toward the tumor nest." (PMID 39119085, 2024). "The NGF secreted from the tumor cells communicated with the NGFR present on the membranes of T cells, which promoted T‐cell proliferation through the activation of the mitotic spindle signaling pathway." (PMID 38204220, 2024). "NGF secreted by tumor cells interacts with NGFR present on the membranes of the infiltrated T cells, thereby promoting the proliferation through the activation of mitotic spindle signals." (PMID 38204220, 2024). "The tumor volume of the overexpressing NGF cell line (143B/NGF) was significantly larger than that of the original 143B cell line." (PMID 38816365, 2024). "Targeting NGF signaling pathways presents an encouraging opportunity for therapeutic intervention in pediatric oncology, with the potential to inhibit tumor growth and improve treatment outcomes." (PMID 39056738, 2024). "The third type of tumor to prove the importance of NGF/TrkA blockage as a possible target for pain relief is sarcoma." (PMID 39766161, 2024). "NGF produced by tumor cells can bind to afferent nerves, especially to transient receptor potential vanilloid 1 (TRPV1)." (PMID 39766161, 2024). "The overexpression of NGF has been shown to promote tumor growth and the expression of M2 macrophage markers in vivo." (PMID 39247831, 2024). "Several authors have demonstrated that NGF released by tumor cells promotes neuritic growth, reduces apoptosis, and increases the proliferation of cancer cells, leading to PDAC aggressiveness." (PMID 39766161, 2024). "Tumor samples collected at the end of the experiment were subjected to IHC, which showed that the tumors in the NGF-treated group were significantly larger than those in the control group." (PMID 39385213, 2024). "In human glioma microvascular endothelial cells, NGF plays a role in tumor angiogenesis by interacting with the α9β1 integrin." (PMID 38375479, 2024).
tumor (continued). "NGF was observed to be co‐localized with NGFR on the membrane of the infiltrated T cells in the tumor tissues of HCC patients." (PMID 38204220, 2024). "The present study elucidated NGF‐NGFR communication inefficiency in the tumor tissues of HCC patients." (PMID 38204220, 2024). "Researchers have demonstrated that inhibiting NGF or its receptor (TrkA) significantly retards tumor development, reduces pain-related activity, and ameliorated bone damage in sarcoma." (PMID 38816365, 2024). "ADIRF, tumor-associated genes CLU, FAM13C, as well as NGF, PRELP, RERG, PTGIS, GPC3 genes were among the top 20 overexpressed genes in EcE stromal cell population." (PMID 39169201, 2024). "In order to further understand the role of NGF‐NGFR communication in PD‐1 mAb anti‐tumor immunotherapy in HCC patients, NGF‐NGFR communication was studied in 29 PD‐1‐positive patients exposed to PD‐1 mAb, 12 non‐responders, and 17 responders." (PMID 38204220, 2024). "For example, neurotrophic factors such as nerve growth factor (NGF) stimulate nerve growth in the tumor microenvironment (TME), leading to sensory and sympathetic nerve infiltration." (PMID 39492832, 2024). "In estrogen receptor-positive breast cancer, NGF inhibits the C2-mediated apoptosis of breast cancer cells by activating the nuclear factor NF-κB and regulates the primary tumor response to tamoxifen." (PMID 39385213, 2024). "NGF contributes to cancer inflammation by cytokines release stimulation and can modulate tumor growth by stimulating cancer cell proliferation, promoting apoptosis, producing pro-angiogenic factors, and inducing the epithelial–mesenchymal transition." (PMID 39056738, 2024). "Together, these results suggested that the tumor cell‐secreted NGF was received specifically by the NGFR expressed in T cells, and NGF‐NGFR communication was inefficient in the tumor tissues of HCC patients." (PMID 38204220, 2024). "Nerve fibers communicate with tumor cells through neuropeptides, such as CGRP or NGF (nerve growth factor), through which they achieve important processes in tumor progression such as angiogenesis and metastasis." (PMID 38674047, 2024). "NGF also activates multiple pathways within the tumor that increase cellular invasiveness such as nuclear factor kappa–light-chain-enhancer of activated B-cells (NF-κB)." (PMID 37834436, 2023). "After NGF knockdown in tumor cells, the amount of neurite outgrowth into tumor tissue was significantly reduced and tumor growth was reduced by approximately 50%." (PMID 37834436, 2023). "Studies in primary and cultured cancer cells have shown that NGF promotes differentiation and stops tumor progression." (PMID 36941697, 2023). "Neurotrophins, such as nerve growth factor (NGF), can be released by leukocytes, such as macrophages and mast cells, to promote an axonogenic switch resulting in tumor innervation." (PMID 36980690, 2023). "NGF promotes the innervation and proliferation of gastric and pancreatic cancerous epithelium and it is responsible for the tumor development." (PMID 36941697, 2023). "Growth factors such as Nerve Growth Factor (NGF) and its precursor proNGF have been shown in our laboratory to play a role in tumor growth and aggressiveness." (PMID 37576898, 2023). "Even at early stages, it has been reported that the release of neurotrophic factors including nerve growth factor, glial cell line-derived neurotrophic factor and brain-derived neurotrophic factor is an essential component of tumor progression." (PMID 37027061, 2023). "For similar reasons, anti-NGF therapy has been suggested as a potential strategy for improving comfort and slowing tumor growth in human oral cancer patients." (PMID 37274254, 2023). "As a result, by increasing the density of nerve fibers, NGF also stimulates sensory nerve fibers and sympathetic nerve fibers to produce connections and form a neuroma-like structure in the tumor, known as Neural reprogramming." (PMID 37007073, 2023).
tumor (continued). "The tumor-derived exosome miR-21-5p stimulated by NGF from PSCs activates the Warburg effect in neurons, upregulates the expression of nociceptor genes, and promotes the PNI." (PMID 37347365, 2023). "The model confirms the experimental observations that a tumor is able to promote nerve formation/elongation around itself, and that high levels of nerve growth factor and axon guidance molecules are recorded in the presence of a tumor." (PMID 36826857, 2023). "For this reason, increasing attention is directed toward NGF and/or TrkA as a therapeutic target for effectively controlling tumor progression." (PMID 37578676, 2023). "The paracrine NGF of tumor cells activates Schwann cell autophagy, enhances the chemical attraction to tumor cells, and accelerates the removal and phagocytosis of myelin debris to promote early axonal and myelin regeneration." (PMID 37347365, 2023). "NGF can promote or suppress tumor growth depending on tumor types, with prominent examples of NGFs from cobra venom inhibiting the growth of Ehrlich’s adenocarcinoma in vivo, but proliferative activity on breast cancer cell line MCF-7." (PMID 38276526, 2023). "Overexpression and secretion of NGF attracts neurons leading to neurite outgrowth into tumor tissue." (PMID 37834436, 2023). "For example, in bone tissue, the release of Nerve growth factor (NGF) from tumor and stromal cells promoted neuropathic sprouting and neuroma formation." (PMID 36400869, 2023). "Meanwhile, tumor cells can produce and release neurotrophic factors like nerve growth factor (NGF) or brain-derived neurotrophic factor to promote tumor innervation." (PMID 37347365, 2023). "Recent progress in NGF research has shown that NGF has a role in carcinogenesis and the pathogenesis of many tumours by regulating cell proliferation, invasion, and therefore cancer cell survival." (PMID 35681586, 2022). "Blockage of the NGF/neurotrophic receptor tyrosine kinase 1 (Trk) pathway impairs tumor growth, prolongs mouse survival, and enhances tumoricidal effect of gemcitabine in spontaneous PDAC mouse models." (PMID 36230914, 2022). "Taken together, these findings indicated that inhibiting the internalization or the binding between NGF and SorCS3 interfered with the tumour suppressor function of SorCS3." (PMID 35393432, 2022). "The earliest and most well-studied of these is NGF which is known to have the ability to increase the survival of the neural cells and also to inhibit both angiogenesis and tumor invasion." (PMID 35056889, 2022). "QRT-PCR showed that the expression of the ACTA2, C1QTNF9, DNAH8, GATM, LBP, and NGF were significantly downregulated in tumor samples." (PMID 36319832, 2022). "Cancer cells can induce the outgrowth of nerves in the tumor microenvironment by the secretion of neurotrophic factors, such as nerve growth factor, and in turn nerves are emerging regulators of cancer initiation, progression, and metastasis." (PMID 35109895, 2022). "While VEGF is already in clinical use, several other potential candidates such as nerve growth factor (NGF) have been suggested as markers of tumor progression and potential targets for future innovative therapies." (PMID 35596772, 2022). "In this case, stimulation of β2-adrenergic receptors on tumour cells makes them secrete NGF which, in a feed-forward loop, attracts even more axons and demonstrates the pro-tumorigenic function of the sympathetic nervous system." (PMID 35269454, 2022). "Murine PNI and cell culture models were used to demonstrate that tumour cells produce NGF, which acts through ATG7 (activated in autophagy 7) to induce autophagy in SCs and promote invasion of the nerve." (PMID 35269454, 2022). "In the same tumor model, the NGF-TrkA axis triggers the epithelial–mesenchymal transition (EMT) and confers resistance to the epidermal growth factor receptor tyrosine kinase (EGFR) inhibitor erlotinib." (PMID 36499024, 2022).
tumor (continued). "The combination of the NGF inhibitor and chloroquine significantly decreased the tumor size compared with that of the other groups." (PMID 35109895, 2022). "In a positive feedback loop, Ach-activated tumour cells produce NGF and recruit more Ach-secreting axons, leading to hyperinnervation and further Wnt activation." (PMID 35269454, 2022). "Subsequently, we used a model of neuroinvasion in nude mice to assess the effect of NGF in vivo on tumor nerve invasion as well as on nociceptive transmission." (PMID 36285300, 2022). "NGF and NGF receptors are important in the progression of some neurological diseases, including tumours." (PMID 35393432, 2022). "The nervous system releases serine into the pancreatic tumour microenvironment, but in the case of serine scarcity, more NGF is produced by PDAC cells by increasing the progression of axons along the tumour." (PMID 36497277, 2022). "The overexpression of CACNA2D1, JUN, GNG4, NGF, MYC, and MAPK4K4, components of the MAPK pathway, is associated with tumor aggressiveness and chemotherapy resistance." (PMID 36344487, 2022). "The neuronal tracking can be mediated by various molecules including chemokines and NGF secreted by the tumor microenvironment." (PMID 35596772, 2022). "The combination of the NGF inhibitor and chloroquine significantly decreased the tumor size compared with that of the control and CQ groups." (PMID 35109895, 2022). "The gold nanocluster-assisted delivery of NGF siRNA (GNC-siRNA) is used to inhibit tumor progression in subcutaneous models, orthotopic models and patient-derived xenograft models." (PMID 35109895, 2022). "Stress-mediated upregulation of nerve growth factor (NGF) secretion by tumor cells was proposed to attract sympathetic nerve growth via “tumor axonogenesis”8." (PMID 35418199, 2022). "NGF has a promoting effect on various cancers, and anti-NGF has been shown to reduce tumor proliferation." (PMID 36406133, 2022). "NGF is one of the well-characterized neurotrophins that can serve as autocrine factor to tumor cells." (PMID 34790909, 2021). "Several studies have shown that nerve growth factor (NGF) is expressed and secreted by tumor and tumor-associated immune cells and reportedly regulates TRP channels." (PMID 35053150, 2021). "NGF facilitates the innervations of the perivascular nerve to regulate blood circulation in the tumor neovessels supplying its metabolic needs." (PMID 35053150, 2021). "The cross talk between tumor cells, endothelial cells and nerves is mediated by growth factors such as nerve growth factor (NGF) which can regulate VEGF and matrix metalloproteinases (MMPs) within the microenvironment." (PMID 34790909, 2021). "In contrast, when mice were injected subcutaneously with C4-2 cells stably expressing NGF cDNA, we found that the tumor size of mice increased." (PMID 33398073, 2021). "Expression of NGF can induce neovascularization around the nerves in turn promoting tumor growth and proliferation." (PMID 34790909, 2021). "AR-tropomyosin receptor kinase (TRK) crosstalk mediated through nerve growth factor (NGF) also promoted tumor growth in ARSI challenged PCa cell lines, and are targetable by NTRK1/TRKA inhibitors." (PMID 34771580, 2021). "JJ012 and JJ012/NGF cells were orthotopically implanted into the right leg tibia and tumor size was monitored by the IVIS system." (PMID 34815382, 2021). "ADBR2-mediated signaling (through local release of NE from SNS nerve fibers or from circulation) in tumor cells can upregulate NGF production which in turn can stimulate NGFR/TrkA signaling in an autocrine loop to promote cell survival by preventing apoptosis." (PMID 34790909, 2021). "The IVIS data confirmed that overexpression of NGF significantly increased tumor growth in the tibia." (PMID 34815382, 2021). "JJ012 and JJ012/NGF cells were orthotopically implanted into the right leg tibia and the tumor size was monitored each week by the IVIS system." (PMID 34283074, 2021).
tumor (continued). "Although nerve tissue also had moderate to strong expression of NGF and TrkA, the authors showed that the expression of NGF was positively correlated with TrkA expression in tumor samples (Spearman’s correlation coefficient = 0.65)." (PMID 34885121, 2021). "Immunohistochemicalstudies in prostate cancer suggested that pro-NGF production by tumour cellsmight drive axonogenesis." (PMID 33465324, 2021). "Activation of PI3K stimulates trafficking of both channels towards the membrane, which increases their membrane expression as well as their ability to be activated or sensitized by NGF and other molecules released by the tumor." (PMID 35053150, 2021). "Meanwhile, in tumor tissues, the overexpression of NGF and hypoxia-inducible factor-1α (HIF-1α) boosts angiogenesis." (PMID 34502019, 2021). "Six days after being given different treatment, tumor size increased gradually in the Control group and the NGF group, but it grew more slowly in the NGF with Verteporfin group as well as in the Ro 08-2750 group." (PMID 34722240, 2021). "NGF plays a multi-functional role in the tumor environment, exerting effects on tumor cell proliferation, survival, apoptosis, angiogenesis and metastasis." (PMID 34283074, 2021). "After treatment for 6 days, tumor size in the NGF with Verteporfin group and the Ro 08-2750 group began to decrease, while it kept increasing in the Control group and the NGF group." (PMID 34722240, 2021). "In summary, the present study sheds light on some mechanisms by which metformin prevents the tumour-promoting effects of NGF in EOC cells." (PMID 33081077, 2020). "There is a number of angiogenic mediators released by MCs in the tumor microenvironment including IL-8, NGF, TNF-α, TGF-β, and urokinase-type plasminogen activator (PA)." (PMID 31256327, 2020). "Metformin blocks the tumour-promoting effects of NGF in EOC cells modulating several oncoproteins such as VEGF, c-MYC and survivin, as well as c-MYC and β-catenin/TCF-Lef transcriptional activity." (PMID 33081077, 2020). "Numerous studies reveal that the high level of NGF in PC is closely correlated with tumour proliferation, tumour cell apoptosis and perineural invasion, especially." (PMID 32294802, 2020). "NGF blockade at early bone sarcoma stages has been shown to relieve tumor-induced bone destruction as well as reduce pain by 40–70%." (PMID 33392191, 2020). "NGF-induced neurons often express tyrosine hydroxylase, suggesting that they deliver catecholamines into the tumor bed." (PMID 33322770, 2020). "In this case, tumor cells secrete NGF and BDNF (brain-derived neurotrophic factor) stimulating nerve growth via their Trk receptors (Tropomyosin-related kinase receptors)." (PMID 32555170, 2020). "There are several studies in which the anti-tumor effects of metformin have been evaluated in-vivo but, unfortunately, working with NGF is more difficult, because the half-life in circulation is only 2.3 h following intravenous injection." (PMID 33081077, 2020). "In PDAC, tumor cells secrete NGF and BDNF, which act on Tropomyosin-related kinase (Trk) receptors to stimulate nerve growth." (PMID 33322770, 2020). "Sensitized nerve fibers are vulnerable to noxious stimuli and tumor-induced and/or released factors such as NGF, endothelins, prostaglandins, protons, bradykinin, and cytokines." (PMID 33392191, 2020). "Overall, our study provides important perspectives on previous publications reporting that both NGS and NGF-based MRD assays can reach a sensitivity of up to one tumor cell per 1,000,000 BM cells (10−6)." (PMID 32824635, 2020). "Early work on nerve growth factor (NGF) found that certain tumor cell types or tissues secrete large amounts of NGF, presumably to recruit neuronal cells for innervation of the growing malignancy." (PMID 32649728, 2020). "Among them, the nerve growth factor (NGF) and the brain-derived neurotrophic factor (BDNF) cause axonal chemoattraction, and IL-6, IL-8, IL1b, and CCL5 foster tumor-associated hyperalgesia." (PMID 30825056, 2019).